RNU7-28P (RNA, U7 small nuclear 28 pseudogene)
Synonyms: U7.28
Gene: Small nuclear RNA gene on chromosome 11 (9,843,815 to 9,843,876, reverse strand). Ensembl gene ENSG00000252568.
Homologues: Orthologues: macaque U7 (92% identical). Paralogues in human: RNU7-13P (92% identical), RNU7-18P (92% identical), RNU7-6P (92% identical), RNU7-7P (92% identical), RNU7-8P (92% identical), RNU7-14P (90% identical), RNU7-22P (90% identical), RNU7-3P (90% identical), RNU7-45P (90% identical), RNU7-11P (89% identical), RNU7-128P (89% identical), RNU7-147P (89% identical), and 140 more.